CREB3L1 (cAMP responsive element binding protein 3 like 1)
Diseases named in the same sentence as CREB3L1 in open-access papers (continued):
Sharing a sentence is not in itself a finding about the gene and the disease.
cancer (continued). "Thus, while PERK induces CREB3L1 in cancer cells that have undergone an EMT, it fails to do so in cells that have not undergone an EMT." (PMID 29057869, 2017). "Moreover, CREB3L1 inhibition resulted in a >400-fold reduction in lung metastases, as measured both by luminescence emitted by metastatic cells in whole lungs, as well as by immunohistochemistry staining for GFP-positive cancer cells in lung sections." (PMID 29057869, 2017). "Besides, no pan-cancer analysis of CREB3L1 has been published to date." (PMID 36171879, 2022).
infection (3 papers, 2021 to 2025). The state of being infected such as from the introduction of a foreign agent such as serum, vaccine, antigenic substance or organism. "In this study, we showed that DOX-mediated apoptosis of OC cell lines and clinical specimens was associated with translocation of CREB3L1 from the cytoplasm to nucleus and the effect was augmented by infection with OVV or treatment with IFN-β." (PMID 34632049, 2021). "The current study establishes that inhibition of cellular proliferation of multiple human OC cell lines to treatment with DOX is augmented by infection with the WR strain of OVV and is associated with nuclear translocation of the CREB3L1 transcriptional factor." (PMID 34632049, 2021). "However, the effect of OVV on CREB3L1 expression and translocation was undetectable or small compared to the reported activation of CREB3L1 in responses to infection with RNA viruses (hepatitis C virus, West Nile virus, and Sendai virus) and murine γ-herpesvirus 68 DNA virus." (PMID 34632049, 2021). "Thus, CREB3L1 appears to play a dual role in TB: under controlled infection, it acts as an immunomodulator limiting excessive pulmonary inflammation, while in severe disease, it may reflect an attempt by the host to amplify inflammatory responses to counteract progressive infection." (PMID 41388607, 2025). "Infection of HeLa cells with wild-type C. burnetii resulted in up-regulation of CREB3L1, which was not seen when the cells were infected with the ΔankG mutant." (PMID 35134097, 2022).
bone cyst (2 papers, 2023). "Eight AFF patients (NS2‐9) without a clinical suspicion of a monogenic bone disorder carried one or more heterozygous VUS with a CADD score ≥ 20 in P4HB, PHEX, TNFRSF11A, CREB3L1, TCIRG1, SERPINH1, LEPRE1, and PLOD2." (PMID 37076969, 2023).
metabolic disease (1 paper, 2022). A congenital disorder (due to inherited enzyme abnormality) or acquired (due to failure of a metabolically important organ) disorder resulting from an abnormal metabolic process. "The broad regulation of neuropeptide synthesis and secretion by Creb3l1 presents a new therapeutic strategy for metabolic diseases." (PMID 35803572, 2022).
CREB3L1 also shares sentences with these, for which no sentence is quoted: lung adenocarcinoma (3 papers); small cell osteosarcoma (3); cervical squamous cell carcinoma (2); chromophobe renal cell carcinoma (2); colon adenocarcinoma (2); esophageal cancer (2); fibrosis (2); head and neck squamous cell carcinoma (2); melanoma (2); prostate adenocarcinoma (2); rectal adenocarcinoma (2); systemic sclerosis (2); thymoma (2); bladder urothelial carcinoma (1); bone sarcoma (1); brain cancer (1); breast invasive carcinoma (1); Bruck syndrome (1); cancers of the kidney (1); chondroblastoma (1); chondrosarcoma (1); chronic kidney disease (1); clear cell carcinoma (1); clear cell kidney carcinoma (1); colitis (1); dermatofibrosarcoma protuberans (1); diabetic nephropathy (1); endometriosis (1); esophageal adenocarcinoma (1); focal segmental glomerulosclerosis (1).
A further 50 diseases each share a sentence with CREB3L1 in 1 paper.